ULBP1 (UL16 binding protein 1)
Diseases named in the same sentence as ULBP1 in open-access papers (continued):
Sharing a sentence is not in itself a finding about the gene and the disease.
cervical cancer (5 papers, 2014 to 2020). A primary or metastatic malignant neoplasm involving the cervix. "Thus, when identifying patients with cervical cancer at increased risk of tumor invasion and/or progression, examining the expression levels of ULBP1 or MICA/B via IHC may have utility." (PMID 25510288, 2014). "Immunohistochemistry analysis revealed that MICA/B and ULBP1 were significantly upregulated in cervical cancer tissues compared to their corresponding normal tissues." (PMID 25510288, 2014). "Multivariate analysis indicated that MICA/B+/ULBP1+ (HR = 0.16, p = 0.015) and ULBP1+ (HR = 0.31, p = 0.024) are independent prognostic factors of disease-free survival in cervical cancer." (PMID 25510288, 2014). "Since their expression increases even in early stages of cervical cancer, MICA/B and ULBP1 expression can be used to identify precursor lesions (i.e., CIN) that are at high risk of developing invasive cervical cancer." (PMID 25510288, 2014). "High expression of either ULBP1 or MICA/B and ULBP1 combined is an indicator of good prognosis in cervical cancer, suggesting their potential utility as prognostic tests in clinical assessment." (PMID 25510288, 2014). "MICA/B, ULBP1, and RAET1E expression was higher in cervical cancer than in low-grade CIN (p < 0.001, p = 0.012, p = 0.013, respectively) and normal cervix (all p < 0.001)." (PMID 25510288, 2014). "Overall, the expression of several NKG2DLs, namely MICA/B, ULBP1, and RAET1E, were increased in cervical cancer patients." (PMID 25510288, 2014). "Invasive cervical cancer tissues had higher MICA/B, ULBP1, and RAET1E expression than CIN or normal cervical epithelial tissues (all p < 0.001)." (PMID 25510288, 2014). "We then performed IHC analysis of MICA/MICB, ULBP1, ULBP2, ULBP3, RAET1E, and RAET1G in 200 cervical cancer specimens, 327 high-grade CINs, 99 low-grade CINs, and 541 matched nonadjacent normal cervical epithelial tissue samples." (PMID 25510288, 2014). "Notably, higher MICA/B and ULBP1 expression correlated with more advanced stages of cervical carcinogenesis, increasing from normal cervical tissue to progressively advanced stages of cervical cancer precursors (low-grade and high-grade CIN) and ultimately to invasive cancer." (PMID 25510288, 2014). "ULBP1 expression was correlated with MICA/B (p < 0.001) and ULBP2 (p = 0.002) expression in cervical cancer." (PMID 25510288, 2014). "This trend of progressively increasing MICA/B, ULBP1, and RAET1E expression corresponded to the phases of cervical cancer progression and was significant according to Spearman’s rank correlation (ρ-value of 0.313 [p < 0.001], 0.285 [p < 0.001], or 0.136 [p < 0.001], respectively)." (PMID 25510288, 2014). "More specifically, MICA/B, ULBP1 and RAET1E expression was significantly increased in cervical cancer tissues, while ULBP2 and ULBP3 expression were higher in low-grade CIN tissues, but lower in high-grade CIN and cervical cancer tissues." (PMID 25510288, 2014). "However, metformin did not induce MICB, ULBP1, ULBP2/5/6 and ULPB3 expression on the surface of human cervical cancer cells." (PMID 32631421, 2020).
melanoma (5 papers, 2021 to 2026). A malignant, usually aggressive tumor composed of atypical, neoplastic melanocytes. "Additionally, TRPM8 modulators increase expression of the NK cell-activating ligand ULBP1, enhancing melanoma susceptibility to NK-mediated cytotoxicity." (PMID 41688418, 2026). "For example, the absence of soluble ULBP1 and MICB were related with better clinical outcome for melanoma patients treated with anti-CTLA-4 or anti-PD-1 antibodies." (PMID 36726591, 2022).
viral infections (5 papers, 2016 to 2025). "ULBP1 has been reported to control bacterial and viral infections, suggesting its potential involvement in controlling Toxoplasma infection." (PMID 40630957, 2025). "NK cells trigger an immune response by recognizing Natural Killer Group 2D (NKG2D) that is expressed on the surface of viral infections or tumor cells, and UL16 binding protein 1 (ULBP1) is one of the ligands recognized by NKG2D on the surface of NK cells." (PMID 40296917, 2025). "TNFAIP3, ULBP1 and TIAM1 were consistently down-regulated by viral infection, while CCL8, CCL11, CXCL11, NCF2, CSF3 and PRKCB were significantly up-regulated after infection." (PMID 28938587, 2017). "The peak of viral infections is between the first and third week, which coincides with maximal serum MICB and ULBP1 concentrations, and with NKG2D downregulation." (PMID 26745675, 2016).
gastric cancer (4 papers, 2020 to 2022). A primary or metastatic malignant neoplasm involving the stomach. "ULBP1 also interacted with NKG2D to improve survival of gastric cancer patients by induction of adaptive immunity." (PMID 35236310, 2022). "Moreover, we investigated the relationship between the expression of EMT markers and ULBP1 on CTCs and gastric cancer cell lines." (PMID 32077634, 2020). "Our results showed that the CTCs of gastric cancer patients exhibited three EMT marker subtypes, and that the expression of ULBP1 was significantly lower on mesenchymal phenotypic CTCs (M+CTCs) than on epithelial phenotypic CTCs (E+CTCs)." (PMID 32077634, 2020). "In this study, we identified CTCs of 41 patients with gastric cancer using Cyttel‐CTC and im‐FISH (immune‐fluorescence in situ hybridization) methods, and tested the expression of EMT markers and ULBP1 (a major member of the NKG2D—natural killer [NK] group 2 member D—ligand family) on CTCs." (PMID 32077634, 2020).
HCMV infection (4 papers, 2014 to 2018). "HCMV infection strongly induces transcription of MICB, ULBP1, and ULBP2 mRNA but prevents their surface expression by intracellular sequestration with HCMV UL16." (PMID 24906157, 2014). "In addition, since ULBP1 is a critical protein in immune elimination of HCMV and also a novel potential target of HCMV-miR-UL-59, we speculated that intensive research on the functions of this newly regulatory relationship will help us to uncover the molecular mechanism of HCMV infection in future." (PMID 28592251, 2017).
lymphoma (4 papers, 2017 to 2018). A malignant (clonal) proliferation of B- lymphocytes or T- lymphocytes which involves the lymph nodes, bone marrow and/or extranodal sites. "In particular, the high expression level of ULBP1 indicates the susceptibility of lymphoma to Vγ9Vδ2-T cell-mediated cytolysis." (PMID 28894450, 2017). "Indeed, UL16-binding protein 1 (ULBP1) is involved in lymphoma susceptibility to γδ T-cell-mediated cytolysis and the blockade of its receptor NKG2D significantly inhibits lymphoma cell killing." (PMID 28713381, 2017). "Our group’s work revealed that ULBP1 was particularly important for leukemia and lymphoma cell recognition by PAg-activated Vγ9Vδ2 T cells." (PMID 29755480, 2018). "Microarray analyses revealed significant upregulation of a multitude of NK-activating and costimulatory ligands across varied b-NHL cell lines and primary lymphoma cells, including ULBP1, CD72, CD48, and SLAMF6." (PMID 29312292, 2017). "Together with previous studies, we reported that NKG2D can bind to its ligands, such as MICA, MICB, and ULBP-1, -2, -3, and -4, which are expressed in different tumors, including leukemia, lymphoma, ovarian, and colon carcinoma." (PMID 28894450, 2017). "Moreover, therapeutic strategies that enhanced the expression of NKG2D or DNAM-1 ligands, such as MICA/B and ULBP1/2, or Nectin-2 and PVR, respectively, potentiated γδ T cell recognition of colon cancer, glioblastoma, multiple myeloma, and lymphoma cells." (PMID 29755480, 2018).
HIV-1 infection (3 papers, 2011 to 2016). The type species of lentivirus and the etiologic agent of acquired immunodeficiency syndrome (AIDS). "It would seem likely that NK cells would be skewed toward killing infected cells since HIV-1 infection leads to increased expression of ICAMs on the infected cell surface, induces expression of ULBP-1 and ULBP-2, and down modulates HLA-A and HLA-B." (PMID 21994772, 2011).
preeclampsia (3 papers, 2019 to 2024). Preeclampsia is a hypertensive disorder of pregnancy that is characterized by new-onset hypertension with proteinuria presenting after 20 weeks of gestation, and depending on mild or severe forms may initially present with severe headache, visual disturbances, and hyperreflexia. "Overexpressed ULBP1 could activate NK cells to regulate disorders including tumors and preeclampsia." (PMID 38481217, 2024). "Taken together, these findings suggest that TNF-α is able to regulate autophagic activity via suppressing NF-κB, which might be the mechanism related to ULBP1 in preeclampsia pathogenesis." (PMID 32626772, 2020).
B-cell lymphoma (2 papers, 2022). "We then treated with metformin the primary cells from a B-cell lymphoma patient (BCL-P2) and observed that it significantly increased expression of ULBP1 and ICAM-1 and tended to increase MICA/B and CD20 expression." (PMID 35079096, 2022).
chronic myelogenous leukemia (2 papers, 2015 to 2022). "To address whether ATF4 regulates ULBP1 in other cell types, we mutated ATF4 in the K-562 chronic myelogenous leukemia cell line and the Jurkat acute T-cell leukemia cell line." (PMID 26565589, 2015).
Cirrhosis (2 papers, 2020 to 2023). A chronic disorder of the liver in which liver tissue becomes scarred and is partially replaced by regenerative nodules and fibrotic tissue resulting in loss of liver function. "High expression of ULBP1 was associated with cirrhosis (p = 0.036)." (PMID 36210637, 2023). "Serum concentrations of the NKG2D ligand ULBP1 were elevated in Gambian patients with HCC compared with either patients with cirrhosis or with healthy controls (median ULBP1 concentrations 2626, 691, and 128 pg/ml, respectively)." (PMID 32656081, 2020).
Ewing sarcoma (2 papers, 2012 to 2020). A small round cell tumor that lacks morphologic, immunohistochemical, and electron microscopic evidence of neuroectodermal differentiation. "Independently, entinostat augmented the expression of ULBP1, HLA, and MICA/B on both rhabdomyosarcoma and Ewing sarcoma cell lines." (PMID 32499867, 2020).
head and neck squamous cell carcinoma (2 papers, 2012 to 2022). A squamous cell carcinoma that arises from any of the following anatomic sites: lip and oral cavity, nasal cavity, paranasal sinuses, pharynx, larynx, and salivary glands. "For example, proteasome inhibition specifically upregulated ULBP2 in Jurkat cells, but ULBP1 in head and neck squamous cell carcinoma (HNSCC) cells." (PMID 23056001, 2012).
liver cancer (2 papers, 2020 to 2024). An epithelial or non-epithelial malignant neoplasm that arises from the liver. "They emphasized that in liver cancer the inhibitors against DNA methyltransferase increased interferons and activated T cells, while the inhibitors against histone methyltransferase increased UL16 binding protein 1 (ULBP1) and activated natural killer cells." (PMID 38540967, 2024).
liver disease (2 papers, 2018 to 2020). "Our results also suggest that ULBP1 is a potential target in immunotherapy against HCV‐induced liver diseases." (PMID 29511613, 2018). "Follow-up of the existing HBV cohort will allow us to assess whether elevated ULBP1 levels may predict the development (as well as the outcome) of malignancy in the setting of HBV-related liver disease." (PMID 32656081, 2020). "To examine whether elevated serum ULBP1 could be derived from diseased hepatocytes rather than exclusively HCC, we examined levels in patients with chronic hepatitis B (CHB), the most important underlying liver disease in The Gambia." (PMID 32656081, 2020).
non-small cell lung carcinoma (2 papers, 2021 to 2024). A group of at least three distinct histological types of lung cancer, including non-small cell squamous cell carcinoma, adenocarcinoma, and large cell carcinoma.
pancreatic carcinoma (2 papers, 2019 to 2023). "In this study, gemcitabine upregulated the expression of MICB, ULBP1, ULBP2/5/6, ULBP3, and PVR in pancreatic cancer cell lines." (PMID 37169953, 2023).
prostate carcinoma (2 papers, 2019 to 2022). A carcinoma that arises from epithelial cells of the prostate gland. "Since tumor cells are recognized by NK cells through an interplay of activating and inhibitory ligands, we decided to evaluate the expression of CD155, CD112, MICA, MICB, ULBP1-2-5-6, PDL-1, and B7-H6 on 22Rv1, LNCaP, and DU145 prostate cancer cells." (PMID 35465350, 2022). "We observed that CD155 and CD112 were expressed at higher levels than MICA, MICB, ULBP1-2-5-6, PDL-1, and B7-H6 on all the prostate cancer cells (∗∗∗p < 0.001)." (PMID 35465350, 2022).
sarcoma (2 papers, 2020 to 2023). A usually aggressive malignant neoplasm of the soft tissue or bone. "We observed that the high expression of DNAM-1 ligand CD155 as well as the high expression of NKG2D ligands ULBP1, ULBP2, and ULBP3 are negatively associated with survival in sarcoma patients." (PMID 32082316, 2020). "The findings showed a positive association between the expression of KDR and ULBP1 and HS6ST2 expression in 11 different types of cancer (in particular, kidney renal papillary cell carcinoma, sarcoma, skin cutaneous melanoma, thyroid carcinoma, and uterine corpus endometrial carcinoma)." (PMID 37932473, 2023).
squamous cell carcinoma (2 papers, 2019 to 2023). A carcinoma arising from squamous epithelial cells. "Either ULBP1 or ULBP2/5/6 overexpression was associated with squamous-cell carcinoma histology, whereas ULBP4 overexpression was associated with younger age and adenocarcinoma histology." (PMID 31827723, 2019). "Interestingly, either ULBP1 or ULBP2/5/6 overexpression was correlated with a squamous cell carcinoma histology, while ULBP4 overexpression was correlated with younger age and adenocarcinoma histology." (PMID 31827723, 2019). "Our data suggested that an antibody type drug targeting ULBP1 or ULBP2/5/6 might be appropriate for the treatment of squamous cell carcinoma whereas one targeting ULBP4 might be useful for treating adenocarcinoma, as more than a half of studied tumors expressed each of these molecules, respectively." (PMID 31827723, 2019). "In most malignant tumors, the KIFscore was found to be positively correlated with ULBP1, MICB, and CD276, among which, CD276 expression was reported to enable squamous cell carcinoma stem cells to evade immune surveillance." (PMID 37711200, 2023).
acquired immune deficiency syndrome (1 paper, 2021). "Similarly, in individuals with acquired immune deficiency syndrome (AIDS), HIV-1 decreases the cell surface expression of MICA, ULBP1 and ULBP2 in infected cells through Nef protein, which decreases the susceptibility of the virus to NK cell-mediated lysis." (PMID 34400893, 2021).
astrocytoma (1 paper, 2011). "Constitutive levels of NKG2D ligands are low in most cells, thus, to examine the effect of U21 upon the surface expression of the NK ligands, we generated U373 astrocytoma cell lines individually stably expressing ULBP1, ULBP2, ULBP3, MICA, or MICB, using retrovirus-mediated gene transfer." (PMID 22102813, 2011).
Autoimmunity (1 paper, 2017). The occurrence of an immune reaction against the organism's own cells or tissues. "Hence, MICA expression is prone to a rapid recognition by NKG2D-bearing IELs, while ULBP1–3 and murine RAE-1 become available only in the event of epithelial polarity breaking, as result of infection or autoimmunity." (PMID 29209320, 2017).
breast tumor (1 paper, 2012). "Most of the NKG2D ligands examined in this study were frequently expressed among the breast tumor cohort: MIC-AB in 50% of the cases; ULBP-1 in 90%; ULBP-2 in 99%; ULBP-3 in 100%; ULBP-4 in 26%; and ULBP-5 in 90%." (PMID 22257486, 2012).
chordoma (1 paper, 2024). Chordomas are rare malignant tumors arising from embryonic remnants of the notochord in axial skeleton. "In vitro, chordoma CSCs express more B7H6, MICA-B, and ULBP1, assessed by percent positivity and mean fluorescence intensity (MFI), as compared to non-CSCs in all cell lines." (PMID 38741774, 2024). "In this study, NK ligands B7H6, ULBP1, and MICA-B are expressed on the surface of a greater quantity of cells and at a significantly increased concentration within the CSC group as compared to the non-CSC group across six chordoma cell lines." (PMID 38741774, 2024).
esophageal cancer (1 paper, 2025). A primary or metastatic malignant neoplasm involving the esophagus. "For example, ULBP1, a NKG2D ligand (NKG2DL), has been found to be downregulated in esophageal cancer." (PMID 40551137, 2025).
laryngeal carcinoma (1 paper, 2023). Carcinoma that arises from the laryngeal epithelium. "In laryngeal cancer, the expression levels of ULBP1/3 correlated with poor prognosis (P < .05), whereas ULBP2 expression was not significantly correlated with prognosis (P = .269)." (PMID 37565867, 2023). "In HNSCC, including tonsil and laryngeal cancers, ULBP2 had the highest expression level, ULBP1 had the highest, lowest, and ULBP3 was in between." (PMID 37565867, 2023). "In tonsil and laryngeal cancers, the immune escape mechanism mediated by KLRK1 and its ligands ULBP1-3 may competitively inhibit KLRK1, owing to insufficient expression/immune cell infiltration of KLRK1 or sufficient secretion of soluble NKG2DLs by tumor cells." (PMID 37565867, 2023).
liver inflammation (1 paper, 2017). "ULBP1 was also selectively elevated on CD4 T cells from patients with HBV-related liver inflammation (serum ALT >60 IU/l)." (PMID 28031333, 2017).
lung adenocarcinoma (1 paper, 2019). A carcinoma that arises from the lung and is characterized by the presence of malignant glandular epithelial cells. "Our results showed that ULBP1 and ULBP2/5/6 are predominantly expressed in lung squamous cell carcinoma, while ULBP4 is expressed in lung adenocarcinoma." (PMID 31827723, 2019). "Interestingly, ULBP1 or ULBP2/5/6 tend to be overexpressed in lung squamous cell carcinoma, while ULBP4 is largely overexpressed in lung adenocarcinoma." (PMID 31827723, 2019).
lupus (1 paper, 2017). "The lack of and/or failure to induce MICA/B and/or ULBP1 in jSLE monocytes is consistent with current concepts of lupus-related myeloid cell abnormalities." (PMID 28944101, 2017).
lupus nephritis (1 paper, 2017). Glomerulonephritis in the context of systemic lupus erythematosus. "However, enhanced cell segregation to inflammatory sites may also contribute to the reduced ULBP1- and/or MICA/B-positivity cells among jSLE monocytes, as sequestration of myeloid cells to renal tissue has been described for patients with active lupus nephritis." (PMID 28944101, 2017).
lymph node metastasis (1 paper, 2014). "In multivariate analysis, FIGO stage, lymph node metastasis, high ULBP1 expression and high combined MICA/B and ULBP1 expression were independent predictors of good prognosis." (PMID 25510288, 2014).
malignant glioma (1 paper, 2014). A grade III or grade IV glioma arising from the central nervous system. "Additionally, transforming growth factor-beta (TGF-beta) selectively downregulates the expression of MICA, ULBP2, and ULBP4, but not MICB, ULBP1, or ULBP3, in malignant glioma cells." (PMID 24885711, 2014).
metastatic disease (1 paper, 2021). "In addition, the expression levels of MIC-A/B and ULBP-1 on RH30 and RH41 cells were low, which is a feature previously shown to be associated with metastatic disease." (PMID 33809981, 2021).
metastatic melanoma (1 paper, 2021). A melanoma that has spread from its primary site to another anatomic site. "The absence of MICB and ULBP-1 in baseline serum, signifying that MICB and ULBP-1 had reduced shedding, is significantly correlated with improved survival in patients with metastatic melanoma treated with immune checkpoint blockade." (PMID 33802954, 2021).